ITGB1BP1 (integrin subunit beta 1 binding protein 1)
Description:
Key regulator of the integrin-mediated cell-matrix interaction signaling by binding to the ITGB1 cytoplasmic tail and preventing the activation of integrin alpha-5/beta-1 (heterodimer of ITGA5 and ITGB1) by talin or FERMT1. Plays a role in cell proliferation, differentiation, spreading, adhesion and migration in the context of mineralization and bone development and angiogenesis. Stimulates cellular proliferation in a fibronectin-dependent manner. Involved in the regulation of beta-1 integrin-containing focal adhesion (FA) site dynamics by controlling its assembly rate during cell adhesion; inhibits beta-1 integrin clustering within FA by directly competing with talin TLN1, and hence stimulates osteoblast spreading and migration in a fibronectin- and/or collagen-dependent manner. Acts as a guanine nucleotide dissociation inhibitor (GDI) by regulating Rho family GTPases during integrin-mediated cell matrix adhesion; reduces the level of active GTP-bound form of both CDC42 and RAC1 GTPases upon cell adhesion to fibronectin. Stimulates the release of active CDC42 from the membranes to maintain it in an inactive cytoplasmic pool. Participates in the translocation of the Rho-associated protein kinase ROCK1 to membrane ruffles at cell leading edges of the cell membrane, leading to an increase of myoblast cell migration on laminin. Plays a role in bone mineralization at a late stage of osteoblast differentiation; modulates the dynamic formation of focal adhesions into fibrillar adhesions, which are adhesive structures responsible for fibronectin deposition and fibrillogenesis. Plays a role in blood vessel development; acts as a negative regulator of angiogenesis by attenuating endothelial cell proliferation and migration, lumen formation and sprouting angiogenesis by promoting AKT phosphorylation and inhibiting ERK1/2 phosphorylation through activation of the Notch signaling pathway. Promotes transcriptional activity of the MYC promoter.
Synonyms: ICAP1; ICAP-1A; ICAP-1B; ICAP1A; ICAP1B; ICAP-1alpha
Tractability: Antibody: UniProt places it where antibodies can reach, with medium confidence; its Gene Ontology location is reachable by antibodies, with medium confidence. PROTAC: ubiquitination databases record sites on it.
Gene: Protein-coding gene on chromosome 2 (9,403,475 to 9,423,891, reverse strand). Ensembl gene ENSG00000119185.
Subcellular location: Nucleus; Cytoplasm; Cytoplasm, cytoskeleton; Cell membrane; Cell projection, lamellipodium; Cell projection, ruffle
Subcellular location (Human Protein Atlas): Nucleoplasm; Cytosol; Nuclear bodies
Gene Ontology:
Molecular function: GDP-dissociation inhibitor activity; integrin binding; protein binding; kinase binding; protein kinase binding
Biological process: activation of protein kinase B activity; blood vessel diameter maintenance; blood vessel endothelial cell proliferation involved in sprouting angiogenesis; cell-matrix adhesion; cellular response to fibroblast growth factor stimulus; cellular response to vascular endothelial growth factor stimulus; integrin activation; integrin-mediated signaling pathway; negative regulation of cell migration involved in sprouting angiogenesis; negative regulation of cell population proliferation; negative regulation of ERK1 and ERK2 cascade; negative regulation of focal adhesion assembly; negative regulation of protein binding; negative regulation of protein kinase activity; negative regulation of protein targeting to membrane; negative regulation of substrate adhesion-dependent cell spreading; positive regulation of cell population proliferation; positive regulation of endothelial cell migration; positive regulation of Notch signaling pathway; positive regulation of phosphatidylinositol 3-kinase/protein kinase B signal transduction; positive regulation of transcription by RNA polymerase II; protein localization to plasma membrane; regulation of GTPase activity; tube formation; cell migration; and 14 more
Cellular component: cell periphery; cytoplasm; cytosol; focal adhesion; lamellipodium; nucleoplasm; nucleus; perinuclear region of cytoplasm; ruffle; cytoskeleton; membrane; plasma membrane
Genetic constraint (gnomAD): Loss-of-function variants: 10 observed, 17.74 expected, observed/expected ratio (o/e) 0.56, 90% interval 0.35 to 0.96. The upper end of that interval is the gene's LOEUF score, 0.96, which puts it in group 4 of 6, group 1 being the genes least tolerant of losing a copy. Missense variants: 162 observed, 184.85 expected, observed/expected ratio (o/e) 0.88, 90% interval 0.77 to 1. Synonymous variants: 76 observed, 69.36 expected, observed/expected ratio (o/e) 1.1, 90% interval 0.91 to 1.33.
Homologues: Orthologues: chimpanzee ITGB1BP1 (100% identical), dog ITGB1BP1 (98% identical), guinea pig ITGB1BP1 (94% identical), mouse Itgb1bp1 (94% identical), rat Itgb1bp1 (94% identical), pig ITGB1BP1 (88% identical), zebrafish itgb1bp1 (78% identical), tropical clawed frog itgb1bp1 (74% identical).
Diseases named in the same sentence as ITGB1BP1 in open-access papers:
ITGB1BP1 is named in the same sentence as 8 diseases in open-access papers, as found by Europe PMC text mining. Sharing a sentence is not in itself a finding about the gene and the disease. The quoted sentences say what the papers report.
gastric cancer (2 papers, 2013 to 2014). A primary or metastatic malignant neoplasm involving the stomach. "The authors also proposed a new mechanism of how AnxA1 regulates the gastric cancer cell invasion through activation FPR/ERK/ITGB1BP1 pathway." (PMID 23431236, 2013). "In gastric cancer patients, the high expression of this protein was related to the promotion of invasiveness and shorter survival, and this relationship occurred through the FPR/ERK/ITGB1BP1 pathway." (PMID 24719523, 2014).
glioma (1 paper, 2025). A benign or malignant brain and spinal cord tumor that arises from glial cells (astrocytes, oligodendrocytes, ependymal cells). "It was reported that ITGB1BP1 can promote the tumor cell migration and invasion, and ITGB3BP was associated with poor prognosis of glioma." (PMID 40731028, 2025).
malaria (1 paper, 2022). Malaria is a serious and sometimes fatal disease caused by a parasite that commonly infects a certain type of mosquito which feeds on humans. "We therefore, suggest further investigation of the disease immune mechanism associated with the SPRY2 and ITGB1BP1 PSGs towards Malaria." (PMID 35428239, 2022).
tumor (3 papers, 2019 to 2025). "However, the role of different spliced transcript variants of ITGB1BP1 and ITGB3BP in focal adhesions and tumor cell migration remains unclear." (PMID 40731028, 2025).
cancer (2 papers, 2022 to 2024). A tumor composed of atypical neoplastic, often pleomorphic cells that invade other tissues. "We previously showed that TLNRD1 and ITGB1BP1 accumulate at the tips of myosin-X (MYO10)-induced filopodia in cancer cells." (PMID 39013281, 2024).
ITGB1BP1 also shares sentences with these, for which no sentence is quoted: adenocarcinoma (1 paper); infection (1); melanoma (1).